INS (insulin)
Diseases named in the same sentence as INS in open-access papers (continued):
Sharing a sentence is not in itself a finding about the gene and the disease.
Insulin resistance (continued). "In addition, obesity associates with insulin resistance (including insulin suppression of lipolysis) and increased fat cell size (FCS)." (PMID 29721017, 2018). "This paradoxical increase in insulin-stimulated Akt phosphorylation during prolonged fasting has previously been observed in obese participants and contradicts a role of proximal insulin signaling in insulin resistance associated with prolonged fasting." (PMID 30183740, 2018). "Intermediate hyperglycemia can result from deficient insulin secretion and insulin resistance." (PMID 29587416, 2018). "Concordantly, our group has shown that the dysregulation of Wnt signaling, driven by changes in the expression of a related family member (SFRP3), is also associated with inflammation, glucose metabolism, and insulin resistance in the skeletal muscle of insulin-resistant humans." (PMID 29721017, 2018). "Impaired insulin signaling in skeletal muscle may subserve insulin resistance in obesity, whereas insulin resistance associated with prolonged fasting is more likely caused by substrate competition." (PMID 30183740, 2018). "Our results suggest that such threshold may be associated with insulin resistance as overweight subjects had normal insulin sensitivity, which may be due to their young age." (PMID 29417372, 2018). "However, C3 mRNA levels were more associated with insulin resistance, and positive correlations with insulin, glucose and homeostasis model assessment-estimated insulin resistance (HOMA-IR) existed." (PMID 30104553, 2018). "Furthermore, several studies have shown that the calcium–calcineurin pathway directly affects insulin-stimulated glucose transport in adipocytes and elevated levels of cytosolic calcium are associated with insulin resistance." (PMID 29380240, 2018). "However, individuals who achieve a minimum of 5% weight loss had significantly lower insulin resistance and decreased fasting insulin levels." (PMID 29587682, 2018). "The different insulin actions (insulin resistance in T2DM vs. insulin deficiency in T1DM) may explain phenotypic differences in DCM26,34." (PMID 29445083, 2018). "Inverse association was noted between insulin resistance and muscle mass resulted from alteration of insulin signaling which could lead to reduced muscle synthesis." (PMID 30533044, 2018). "RBP4 was found to interrupt the insulin signaling cascade causing insulin resistance." (PMID 29747616, 2018). "Liver steatorrhea is strongly associated with insulin resistance, so the effect of mitoQ to improve liver function may contribute to the decrease in demand for insulin in our HF‐fed model." (PMID 29864244, 2018). "Lipid-induced insulin resistance has been associated with inflammation in epidemiological studies, and by means of different models, several authors have demonstrated that induction of NF-κB activation reduces net insulin-stimulated glucose uptake." (PMID 30598026, 2018). "Also, IL-13 has been shown to promote insulin secretion in pancreatic beta-cells, which is associated with compensatory hyperinsulinemia aimed to counteract hyperglycemia and insulin resistance." (PMID 29675435, 2018). "Previously it was thought that the associated insulin resistance might impair glucose delivery to the lamellar tissues, or affect blood flow; however, it now appears to be a direct effect of insulin (although other factors may also play a role)." (PMID 30519508, 2018). "Insulin resistance is associated with continuous exposure to high concentrations of insulin." (PMID 30044398, 2018). "We have since demonstrated that hyper-stimulation of podocytes with insulin also causes insulin-resistance, by promoting IR degradation, although nephrin expression is also required for selective downstream responses; including glucose uptake and reorganization of filamentous actin." (PMID 30524379, 2018).
Insulin resistance (continued). "In addition, IL-1β, IL-6, and many other pro-inflammatory mediators have been implicated in defective insulin signaling, leading to insulin resistance and eventually T2DM." (PMID 30249283, 2018). "Insulin resistance, insulin secretion and obesity are the most prevalent underlying causes of T2D and thus, much interest has been to identify potential related genes involved and possible mutations that may confer susceptibility to the disease." (PMID 29751826, 2018). "Previous studies have shown that in adipocytes, endoplasmic reticulum stress may lead to pathway dysfunction in insulin signaling, which causes adipocyte insulin resistance." (PMID 29765322, 2018). "Moreover, HA had the lowest body mass index (BMI), WC, higher insulin sensitivity, and lower insulin resistance, but the associations of these parameters with serum 25(OH)D concentrations were not investigated." (PMID 32153911, 2018). "However, Tg HFHS INS was increased, indicating the presence of hyperinsulinemia associated with insulin resistance and its cumulative effect." (PMID 29682407, 2018). "Abnormal insulin signaling, advanced glycation end-products, and oxidative stress caused by hyperglycemia and insulin resistance may promote the pathological interaction between diabetes and atherosclerosis." (PMID 30287742, 2018). "It is considered that high magnesium intake may have greater effects on overweight individuals, who are prone to insulin resistance and are more susceptible to the effects of magnesium on improving insulin sensitivity." (PMID 28749415, 2017). "In addition, CLA has been linked with reduced insulin signaling in cultured adipocytes and mice, suggestive of insulin resistance." (PMID 28245284, 2017). "TNF-α could reduce insulin sensitivity to its receptor and then be implicated in the process of insulin resistance, ultimately exacerbating liver steatosis." (PMID 28349964, 2017). "Glucose tolerance defects were associated with higher insulin levels and insulin resistance." (PMID 28801594, 2017). "In addition, FBG, insulin, and insulin resistance decreased in postmenopausal women at risk for osteoporosis following long-term supplementation with genistein extracts." (PMID 28338639, 2017). "Secondly, elevated circulating insulin levels in T2DM with insulin resistance may influence thyroid carcinoma risk mediated by insulin receptors overexpressed by cancer cells, suggesting that insulin may play a role in thyroid carcinogenesis." (PMID 29228629, 2017). "Considering the epidemic expansion of obesity and type 2 diabetes in this beginning century, two pathologies associated with an insulin-resistance state, the identification of new molecules capable of improving insulin action is of considerable medical interest." (PMID 29203791, 2017). "Adipocyte-derived hormones may affect insulin sensitivity by modulating insulin signaling pathways and therefore may serve as potent indictors of the development of insulin resistance and risk for cardiovascular disease." (PMID 28448547, 2017). "Protein restriction during gestation and/or lactation also resulted in unfavorable intergenerational effects on biometric parameters (i.e., body mass and fat mass) and on glucose, insulin, and leptin metabolism, thereby causing insulin resistance in F1 and F2 adult rat progeny." (PMID 28750655, 2017). "Such biological mechanisms not only promote epidermal hyperplasia in psoriasis, but may also antagonize insulin signaling, alter adipokine expression, and increase risk of insulin resistance and obesity." (PMID 28496169, 2017). "Insulin resistance causes increased insulin secretion by beta cells, and the higher local insulin concentration may induce fat deposition." (PMID 28742102, 2017). "In addition to DAG, increased FFAs supply can raise intracellular ceramides, which induce inflammation-associated insulin resistance by impairing insulin-mediated Akt activation in muscle." (PMID 28261091, 2017).
Insulin resistance (continued). "The association between childhood height growth and insulin resistance may reflect reverse causality; insulin has growth promoting properties, and higher insulin concentrations in childhood may increase height growth." (PMID 27823768, 2017). "Insulin resistance has been known as one of the key cause for type 2 diabetes, so enhancing the insulin sensitivity could be an effective method to treat type 2 diabetes." (PMID 28432282, 2017). "Such mode of malnutrition resulted in expression of early markers of insulin resistance and metabolic disease risk, including alterations in adipocyte cell size and expression levels of several insulin-signalling proteins through post-transcriptional mechanisms." (PMID 28273874, 2017). "Insulin resistance was connected to a higher consumption of fish-related fats, whereas high concentrations of insulin might be associated with a high risk of DAT." (PMID 28418899, 2017). "Disentangling such a specific signature of intestinal microbiota involved in insulin resistance shifts might help to apply approaches aiming to better predict loss of insulin sensitivity and design targeted microbiota-based interventions in obese humans." (PMID 29166392, 2017). "Thus, insulin insensitivitydescribed as insulin resistance with its associated abnormalitieshas become a major challenge and has prompted pharmaceuticalcompanies to search for new insulin sensitizing agents." (PMID 29379255, 2017). "In CTG, the significant reduction of ABFat and waist/hip ratio, both related to insulin resistance and cardiovascular risk, could be due to an improvement of insulin profile." (PMID 29147070, 2017). "Insulin resistance in itself is an insufficient cause of type 2 diabetes, because of the pancreatic beta cells’ ability to compensate for the prevailing level of insulin resistance by increasing insulin secretion." (PMID 27933333, 2017). "Some researches 43, 44, 45, 46 have shown that chronic viral infections, such as HBV, may decrease the tissue response to insulin, thereby causing insulin resistance." (PMID 28557334, 2017). "Usually, glucose intolerance is associated with insulin resistance and insulin secretory defects in aging humans although other factors may contribute to the development of insulin resistance with age, such as obesity and lack of physical activity." (PMID 28961383, 2017). "The results showed that MDG-1 could increase the sensitivity of insulin and ameliorate insulin resistance caused by hyperlipidemia." (PMID 28885549, 2017). "Additionally, in obesity there are elevated levels of growth hormones (i. e. insulin and insulin like growth factor-1) as a consequence of the insulin resistance, which is also causally linked to dysfunctional adipose tissues, especially VATs." (PMID 28886117, 2017). "Diets rich in refined carbohydrates induce a rapid increase in blood glucose concentrations with a high demand for insulin from the pancreatic β-cells, which in turn may increase the risk of insulin resistance." (PMID 28753929, 2017). "However, in AD brain there is a dysregulation of nutrient metabolism, linked to insulin resistance, where a role for insulin treatment to improve cognition has been proposed." (PMID 28626421, 2017). "Mice with liver-specific inactivation (L-SACC1) or with global null mutation of Ceacam1 (Cc1−/−) exhibit impairment in insulin clearance leading to chronic hyperinsulinemia and systemic insulin resistance (owing to downregulation of insulin receptor expression)." (PMID 28184213, 2017). "The disruption of brain insulin signaling (insulin resistance) might confer risk for “food use” disorders through coordinated dysregulation of DA reward." (PMID 28824395, 2017). "As adiponectin is very important in the regulation of insulin sensitivity and metabolism, it might be the cause of insulin resistance and change PFAA profiles in diabetic patients." (PMID 28287627, 2017).
Insulin resistance (continued). "Gene GRN, which presented associations with the 46 traits (p-value ≤ 1.63 × 10−16), HOMA-IR (p-value ≤ 2.28 × 10−29) and insulin (p-value ≤ 7.89 × 10−10), has been reported to associate with insulin resistance in type 2 diabetes patients and the blood insulin levels." (PMID 29040274, 2017). "Additionally, it would be interesting to measure insulin sensitivity in time (i.e. with age) in the same set of calves to study the discovered biomarkers and their association with the development of insulin resistance with age." (PMID 28617863, 2017). "The possible mechanism was associated with insulin sensitivity and insulin resistance." (PMID 29125537, 2017). "Further physiologic evidence suggests that insulin resistance may be on the causal pathway linking BMI and OV due to the known stimulatory effect of insulin on ovarian thecal cells." (PMID 28620546, 2017). "Our current study results are supported by a recent cross-sectional study of ours showing that great numbers of sit-to-stand transitions accumulated throughout the day are associated with lower fasting insulin and lower insulin resistance a similar demographic population." (PMID 29190761, 2017). "Furthermore, we aimed to compare the immunoreactive and bioactive leptin levels associations with parameters of insulin resistance and insulin secretion in obese children and adolescents." (PMID 28542631, 2017). "It has been hypothesized that an abnormal insulin signal transduction may cause insulin resistance, which induces anomalous ovarian steroidogenesis." (PMID 28348586, 2017). "Thus, factors associated with systemic insulin resistance modulate podocyte IR levels, attenuating insulin-stimulated phosphorylation cascades." (PMID 28852804, 2017). "Such an endothelial dysfunction may relate to the development of insulin resistance causing an imbalance between vasodilator and vasoconstrictor effects of insulin." (PMID 28399917, 2017). "Based on the correlation analysis between weight loss and metabolic changes, the annual declines in CRP, insulin, triglyceride, blood sugar, and insulin resistance index were positively correlated with weight loss, and the correlation coefficients were statistically significant." (PMID 28115972, 2017). "With remission of T2DM in both groups, RYGB could modulate the expression level of many peripheral blood miRNAs associated with lipid metabolism, insulin secretion, beta-cell function, and insulin resistance." (PMID 28273212, 2017). "Because of the presence of insulin resistance, we examined the major target organs of insulin and relevant genes that might cause insulin resistance." (PMID 28367331, 2017). "Maternal blood glucose or insulin-induced fetal hyperinsulinemia might cause hyperplasia or hyperactivity of pancreatic β cells, leading to glucose tolerance abnormalities or insulin resistance." (PMID 29191195, 2017). "METAP2, which showed strong association with the 46 traits (p-value ≤ 2.62 × 10−20), HOMA-B (p-value ≤ 3.14 × 10−32), HOMA-IR (p-value ≤ 3.17 × 10−17) and insulin (p-value ≤ 8.61 × 10−10), has demonstrated associations with insulin resistance and insulin levels." (PMID 29040274, 2017). "It is currently argued that metabolic insults such as insulin resistance, prolonged hyperglycemia, and increased free fatty acids (depletion of calcium levels in the ER) lead to excessive stimulation of insulin production by associated β-cells with the accumulation of proinsulin in the ER." (PMID 29204450, 2017). "Thus, a higher value of HOMA-IR and a lower value of QUICKI mean higher levels of insulin or glucose and an increased risk of insulin resistance." (PMID 29191195, 2017). "In future studies it may be appropriate to use a longer dietary intervention to allow greater insulin resistance to develop, in order to tease out the full effect on insulin sensitivity caused by 25(OH)D deficiency." (PMID 28880231, 2017).
Insulin resistance (continued). "In addition, Ccr5 has been implicated in the development of insulin resistance, which further illustrates the role of MI in improved insulin sensitivity." (PMID 28212289, 2017). "This review summarizes the emerging evidence that supports the concept of vascular endothelial regulation of obesity-associated insulin resistance in classic targets of insulin, including fat, liver, and skeletal muscles, and highlights the unanswered questions for future research directions." (PMID 28848738, 2017). "Insulin resistance, and the associated increased insulin levels, might also contribute to excessive ROS production in diabetic wounds, as insulin has been reported to induce NOX-produced ROS in human skin fibroblasts ex vivo." (PMID 29036938, 2017). "Furthermore, insulin resistance was prevented by antioxidant treatment, demonstrating a causal role for ROS in deterioration of insulin sensitivity." (PMID 28545081, 2017). "CLW improved the diabetic diagnostic criteria by reducing hepatic insulin resistance by potentiating hepatic insulin signaling (pAkt➔pGSK-1β) and lowering hepatic triglyceride contents by increasing the phosphorylation of AMPK in non-obese type 2 diabetic rats." (PMID 29104217, 2017). "Since muscle is the primary tissue contributing to whole-body insulin-mediated glucose disposal, sarcopenia and sarcopenic obesity may be important causal factors in insulin resistance." (PMID 28932748, 2017). "It was not established whether the elevated BCAA concentrations in obese insulin resistant individuals were the cause or an effect of insulin resistance." (PMID 28713581, 2017). "In the obese state, high circulating concentrations of nutrients and cytokines promote target of rapamycin (TOR) activity in adipose tissue, which inhibits insulin signaling and causes insulin resistance through different mechanisms, including S6K1 kinase signaling." (PMID 28801592, 2017). "Importantly, the dysfunction of insulin-regulated GLUT4 trafficking is strongly linked with peripheral insulin resistance and type 2 diabetes in human." (PMID 28529958, 2017). "Thus, cats from our cat population, that return from overweight to normal weight have a minimized risk for insulin resistance and show normal insulin sensitivity, even if their insulin sensitivity was slightly decreased when they were overweight." (PMID 28629451, 2017). "We saw some indication of causality of insulin resistance and fasting insulin levels in grip strength in inverse-variance and median-weighted analyses, although the considerable heterogeneity in inverse-variance weighted results warrants a cautious interpretation." (PMID 29313844, 2017). "The role of BCAA has been implicated in the insulin resistance and insulin secretion." (PMID 28698587, 2017). "There is extensive literature describing adiponectin as an adipokine that is associated with insulin sensitivity and vascular wall anti-inflammatory activity in type 2 diabetes, and showing that lower levels of adiponectin are associated with insulin resistance in type 2 diabetes." (PMID 28587667, 2017). "The process of insulin resistance is associated with defects in insulin signalling downstream of insulin receptor (INSR), insulin Receptor Substrate 1/2 (IRS-1/2), Phosphoinositide 3-Kinase (PI3K)/AKT Serine/Threonine Kinase (AKT) and Glucose Transporter 4 (GLUT4)." (PMID 29050364, 2017). "In addition, insulin resistance is also associated with a decreased vasodilatory response to insulin in peripheral tissue and an increased vasoconstrictor response to various vasopressors, which mainly results the increase of systolic blood pressure." (PMID 27412111, 2016). "However, reports on associations between insulin secretion or insulin resistance and 25(OH)D have been inconsistent among different racial groups." (PMID 27413370, 2016).